TRIM58 (tripartite motif containing 58)
Diseases named in the same sentence as TRIM58 in open-access papers (continued):
Sharing a sentence is not in itself a finding about the gene and the disease.
tumor (21 papers, 2017 to 2025). "In this study, we demonstrate that TRIM58 is frequently downregulated by promoter methylation in ccRCC tissues, associated significantly with tumor nuclear grade and poor patient survival." (PMID 33816562, 2021). "Restored expression of TRIM58-WT in A549 cells was associated with a reduced tumor volume and weight in vivo." (PMID 27926516, 2017). "In addition, the overexpression of TRIM58 significantly inhibited the growth and tumor causing nature of OS cells of osteoma." (PMID 34222000, 2021). "However, the molecular mechanisms underlying the tumor-suppressive function of TRIM58 remain unknown and might be different from those involved in erythropoiesis." (PMID 27926516, 2017). "TRIM58 is an E3 ubiquitin ligase that plays a significant role in regulating various cellular processes, including tumor progression." (PMID 40508156, 2025). "Another study investigated TRIM58 overexpression in nude mice, demonstrating a notable decrease in tumor growth and weight, along with an elevation in tumor cell apoptosis." (PMID 40936722, 2025). "Concerning tumor formation and fiber deposition, TRIM58 was one of the utmost hypomethylated genes in IPM." (PMID 40676219, 2025). "Firstly, we examined the protein expression of TRIM58 via IHC method in surgical samples of NSCLC tumor and matched adjacent normal tissues." (PMID 36644609, 2023). "Consistently, transwell assay confirmed that tumor cells with promoted TRIM58 expression demonstrated suppressed cellular mobility and invasiveness, and vice versa." (PMID 36644609, 2023). "And, further detailed experiments depicted novel mechanism that TRIM58 exhibited tumor inhibitory effects via interaction with ZEB1." (PMID 36644609, 2023). "Wound-healing assay results suggested that TRIM58 overexpression significantly reduced cellular migration, and TRIM58 shRNA treated tumor cells exhibited enhanced mobility." (PMID 36644609, 2023). "As for the functions of TRIM58 in cancer pathogenesis and progression, previous studies have been suggested that TRIM58 takes part in the modulation of tumor microenvironment." (PMID 36644609, 2023). "Through binding with ZEB1 protein, TRIM58 enhanced ZEB1 protein degradation via ubiquitin-proteasome pathway so that TRIM58 was capable of minimizing ZEB1-mediated promotion of tumor migrated and survival capability." (PMID 36644609, 2023). "Previous study reported that TRIM58 suppresses the tumor growth in tumor by inactivation of β-catenin signaling via ubiquitination." (PMID 36534449, 2022). "It indicated that TRIM28 was an oncogene, while TRIM58 is more likely to be a tumor suppressor gene." (PMID 36461099, 2022). "Recent studies have highlighted the possible role of TRIM58 as a tumor suppressor gene, which degrades β-catenin through ubiquitination, resulting in the inactivation of β-catenin signaling." (PMID 36461099, 2022). "In summary, the overexpression of TRIM58, a potential tumor suppressor gene inhibited cell proliferation and migration and promoted cell apoptosis." (PMID 34434284, 2021). "TRIM58 exerts a clear tumor suppressive activity in CRC mainly through its critical role in limiting Wnt/β-catenin dependent EMT." (PMID 33066016, 2020). "In contrast, reduced expression of the tumor suppressive TRIM58 is thought to be an eligible marker for early CRC detection." (PMID 33066016, 2020). "In contrast to TRIM29, TRIM58 represents a tumor suppressive member of the TRIM family which is characteristically downregulated in CRC tumors." (PMID 33066016, 2020). "To better elucidate the molecular mechanisms of tumor suppression by TRIM58, we performed microarray analysis to determine the effects of stable TRIM58 overexpression on the A549 cell transcriptome." (PMID 27926516, 2017). "Further analyses of the direct Ub-ligase targets involved in the TRIM58-activated tumor suppressive pathway are needed to identify alternative preventive and/or therapeutic strategies for LADC." (PMID 27926516, 2017).
tumor (continued). "In both our panel of LADC cases and a publicly available data set (TCGA), TRIM58 was consistently silenced via hypermethylation in a tumor-specific manner even in the early stages of tumorigenesis and regardless of smoking status." (PMID 27926516, 2017). "TRIM58 acts as a tumor suppressor in CRC through the promotion of RECQL4 ubiquitination and inhibition of the AKT signaling pathway and may be investigated for the successful treatment of CRC." (PMID 37516854, 2023). "Western blot and RT-PCR experiments also suggested that TRIM58 silencing tend to increase the stem-like cellular phenotype of these tumor cells, as both protein and mRNA expression of stem-cell marker ALDH1 and CD44 demonstrated notably increase in tumor cells treated by TRIM58 shRNAs." (PMID 36644609, 2023). "Functional experiments demonstrated that TRIM58 suppression enhanced malignant biological behaviors including cellular survivability, migration, and invasion, as well as stem-like cellular phenotype of tumor cells." (PMID 36644609, 2023). "In addition, transfection with overexpression vector of TRIM58 markedly suppressed tumor growth in vivo." (PMID 36644609, 2023). "TRIM58 expression in clinical tumor tissue samples and cancer cell lines was examined." (PMID 36644609, 2023). "TRIM58 expression was characteristically decreased in NSCLC tumor tissues and cancer cell lines." (PMID 36644609, 2023). "It has been reported that TRIM58 may inhibit tumor growth through interaction with pyruvate kinase M2 or beta-catenin signaling." (PMID 36461099, 2022). "In both, LUSC and LUAD, TRIM58 was hypermethylated in tumor tissues compared to normal tissues." (PMID 34434284, 2021). "TRIM58 was coordinately hypermethylated and downregulated in lung tumors compared to normal tissue, indicating that it may be a potential tumor suppressor gene." (PMID 34434284, 2021). "Among which, the hypermethylation of ZNF804A, ZFP82, TRIM58, SOX17, and C12orf42 were all noted to be significantly associated with tumor-related pathways, including calcium signaling pathways, neuroactive ligand-receptor interaction, glycosynthetic ganglion series and intercellular junctions." (PMID 33833773, 2021). "Interestingly, ectopic expression of TRIM58 in CRC cells exclusively interfered with tumor cell invasion mainly through inhibition of EMT and MMP regulation, without affecting other malignant properties, such as cell proliferation or migration." (PMID 33066016, 2020). "The ability of TRIM58 to suppress tumor formation in vivo was investigated using tumor xenograft experiments in which subcutaneous tumor growth was compared among severe combined immunodeficient (SCID) mice transplanted with different stable A549 transfectants." (PMID 27926516, 2017). "Moreover, western blotting of the tumor showed that TRIM58 inhibited the expression of RECQL4." (PMID 37516854, 2023). "Many studies revealed that TRIM58 could act as a tumor suppressor." (PMID 34222000, 2021). "Therefore, it remains unclear whether TRIM58 plays different tumor suppressive roles in the lung and liver." (PMID 27926516, 2017). "In this study, we discovered that TRIM58 was significantly suppressed in NSCLC clinical samples and tumor cell models." (PMID 36644609, 2023). "The downregulation of TRIM58 and upregulation of RECOL4 were observed in human CRC tissue, and TRIM58 demonstrated antitumor effects in CRC-induced tumor growth in a mouse model." (PMID 37516854, 2023). "And, TRIM58 interacted with ZEB1 to facilitate ZEB1 protein degradation via UPP, which resulted in the exacerbation of NSCLC tumor expansion, invasion, and metastasis." (PMID 36644609, 2023). "TRIM58 belongs to the tripartite motif protein (TRIM) family of E3 ubiquitin ligases and is considered a candidate tumor suppressor." (PMID 35445910, 2022).
tumor (continued). "It was found that the expression level of KCTD12, SIAH1, TRIM58, UBE2S, and UBE2T were significantly decreased in tumor tissue compared with the normal tissue, but TRIM47 was upregulated." (PMID 36534449, 2022). "Correlations between recurrence and TRIM58, FAM84B, and ELOVL2 expression were analyzed in univariate analyses as well as in multivariate tests adjusted for age, sex, tumor location, extent of resection, and, most notably, histology." (PMID 35445910, 2022). "TRIM58 plays a critical role of tumor suppressor by limiting Wnt/β-catenin dependent EMT; indeed, the recovery of TRIM58 reduces tumor invasion." (PMID 33673719, 2021). "In contrast to the oncogenic action of the TRIMs described so far, TRIM67, TRIM58 and TRIM8 are downregulated in CRC, playing a tumor suppressor role." (PMID 33673719, 2021). "Reduced expression levels of some tumor suppressive TRIMs can result from increased methylation of the corresponding gene promoters as described for TRIM33 and TRIM58." (PMID 33066016, 2020). "Because TRIM58 was silenced in most LADC cases even at early stages, we evaluated proliferation and tumor formation in those cells both in vitro and in vivo." (PMID 27926516, 2017). "Next, we performed cycloheximide (CHX) chase assay to evaluate protein degradation velocity in tumor cells treated with or without TRIM58 overexpression vectors." (PMID 36644609, 2023). "Real-time PCR quantification suggested that mRNA expression of TRIM58 was significantly reduced in tumor tissue, compared with normal counterparts." (PMID 36644609, 2023). "It was also observed that TRIM58 was negatively correlated with the mTORC1 signaling pathway (P<0.001; FDR<0.001; NESLUSC=−2.61; P<0.001; FDR<0.001; NESLUAD=−2.32), further indicating a tumor suppressor role of TRIM58." (PMID 34434284, 2021). "The current study found that AUF1 knockdown significantly increased TRIM58 expression, and knockdown of TRIM58 partly rescued the reduced proliferation and invasion of IHH4 and TPC1 cells by AUF1 knockdown, indicating that TRIM58 also functions as a tumor suppressive effect in PTC cells." (PMID 34222000, 2021). "In non-tumorous lung tissues, cytoplasmic TRIM58 staining was observed in alveolar epithelial cells, especially type II cells, whereas almost no TRIM58 staining was observed in LADC tumor cells, irrespective of the smoking status and tumor stage." (PMID 27926516, 2017). "As TRIM58 expression was positively correlated with M2-polarized macrophage and mast cells in KRAS-driven lung adenocarcinoma tumor tissues, which suggested that TRIM58 might facilitate the infiltration of immune cells in tumor microenvironment and enhance antitumor immune reaction." (PMID 36644609, 2023).
cancer (18 papers, 2011 to 2025). A tumor composed of atypical neoplastic, often pleomorphic cells that invade other tissues. "Recently, it has been reported that TRIM58 expression is associated with poor survival in several human cancers." (PMID 37516854, 2023). "Previous reports have elucidated that TRIM58 is associated with poor prognosis in human cancers." (PMID 37516854, 2023). "Hence, TRIM58 methylation may represent a possible early diagnostic target for cancer." (PMID 37516854, 2023). "TRIM58, an E3 ubiquitin ligase and a member of the tripartite motif protein family, is a potential prognostic marker that indicates poor prognosis in cancer." (PMID 37516854, 2023). "Several studies have discovered that TRIM58, a member of tripartite motif protein family, shows antitumor effect in multiple types of cancer." (PMID 36644609, 2023). "Consistent with previous results, TRIM58 was also down-regulated in various cancers, and the expression of its coding protein in liver tumor tissues is reduced." (PMID 36461099, 2022). "Almost all TRIM58 methylation subtypes are significantly negatively correlated with their expression levels in various cancers, such as LIHC and COAD patients." (PMID 36461099, 2022). "Meanwhile, NOL4, PAX6, TRIM58, and ZNF382 promoter methylation was also associated with the occurrence of many cancers." (PMID 31956659, 2019). "The Δβ values of ALX3, NPTX2, and TRIM58 for five low-survival-rate cancers." (PMID 39944136, 2025). "The Δβ values of ALX3, NPTX2, and TRIM58 for five low-survival-rate cancers by stage." (PMID 39944136, 2025). "It has been demonstrated that abnormal methylation of TRIM58 may lead to down-regulation of its expression, which leads to increased aggressiveness of cancer cells and reduced survival rate of cancer patients." (PMID 36461099, 2022). "Immunohistochemical results further demonstrate the role of TRIM28 and TRIM58 in cancer." (PMID 36461099, 2022). "Aberrant methylation of TRIM58 has become a biomarker in multiple cancer prognostic models." (PMID 36591255, 2022). "On the contrary, TRIM23, TRIM61 and TRIM58 have lower expression in cancer." (PMID 36461099, 2022). "Notably, the expression levels of TRIM58 were negatively correlated with methylation levels in various cancers except KIRC." (PMID 36461099, 2022). "There are reports that TRIM58 plays a role in a variety of cancers." (PMID 36534449, 2022). "In contrast, TRIM58 was ubiquitously low expressed in 11 cancers." (PMID 36461099, 2022). "As a member of the same subfamily of TRIM62 (C-IV-1), it was hypothesized that TRIM58 may regulate the malignant phenotype of cancer." (PMID 34434284, 2021). "In addition, TRIM58 or TRIM23 exhibited lower expression in multiple cancer types." (PMID 36461099, 2022). "The best combination of common methylation biomarkers derived from the five initial cancer types were ALX3, NPTX2, and TRIM58." (PMID 39944136, 2025). "Prediction results of independent prediction models for the five low-survival-rate cancers by using the optimal biomarker combination (ALX3, NPTX2, and TRIM58)." (PMID 39944136, 2025). "Prediction results of the constructed universal model for validating the five additional cancers by using the optimal biomarker combination (ALX3, NPTX2, and TRIM58)." (PMID 39944136, 2025). "TRIM58, a member of TRIM family, containing a RING motif, a B box type 1 and 2, and a coiled-coil domain in its N-terminal region, has been identified as an E3 ubiquitin ligase and considered as an important regulator in several types of cancers." (PMID 36644609, 2023). "TRIMs 3, 8, 13, 16, 21, 62 are downregulated in many of the main cancers worldwide (breast, gastric, liver, lung, osteosarcoma, prostate, kidney), while some TRIMs are under-expressed in a cancer-specific way (e.g., TRIM15 in gastric cancer, TRIM26 in liver, TRIM58 in lung)." (PMID 33673719, 2021).
cancer (continued). "However, the role of TRIM58 in NSCLC metastasis and progression, especially in cancer cellular EMT process has not been clearly elucidated." (PMID 36644609, 2023).
neurodegenerative disease (1 paper, 2024). A disorder of the central nervous system characterized by gradual and progressive loss of neural tissue and neurologic function. "SNCA plays a critical role in synaptic function and is implicated in neurodegenerative diseases, and TRIM58 is essential for proper red blood cell development." (PMID 39944919, 2024).
TRIM58 also shares sentences with these, for which no sentence is quoted: amyotrophic lateral sclerosis (1 paper); autoimmune disease (1); Cachexia (1); Clear Cell Renal Cell Carcinoma (1); head and neck carcinoma (1); Non-alcoholic Fatty Liver Disease (1); non-small cell lung carcinoma (1); renal carcinoma (1); stomach cancers (1).